WNT3A (Wnt family member 3A)
Diseases named in the same sentence as WNT3A in open-access papers (continued):
Sharing a sentence is not in itself a finding about the gene and the disease.
infection (continued). "Indeed, analysis of cytosolic and nuclear β-catenin levels confirmed this and showed that infection of cells with influenza viruses resulted, similar to Wnt3a stimulation, in accumulation of cellular β-catenin protein, mostly in the nucleus." (PMID 24767605, 2014). "Notably, the infection of the pantropic vesicular stomatitis virus G (VSV-G) Vpp was not altered by either the loss or overexpression of Wnt3a, indicating the specificity of Wnt3a in SARS-CoV-2 entry." (PMID 38203386, 2023). "Infection with ST decreased the proliferation genes PCNA, Ki67, and Cyclin; the ISC marker gene Lgr5; the quiescent ISC marker gene Bmi1; the Goblet cell marker gene Muc2; the Paneth cell marker gene Lyz1; and Wnt3a mRNA levels (p < 0.05)." (PMID 38540864, 2024). "The infected mice exhibited increased mRNA levels of canonical (Wnt1, Wnt2, Wnt3, and Wnt3a) and noncanonical (Wnt5a) Wnt molecules, receptors (Fz1 and Fz5) and the Wnt signalling target gene Sox9 in hepatocytes at 6 and 12 weeks post-infection." (PMID 28331224, 2017). "We found that stimulation of primary hepatocytes with Wnt3A induced a greater-than-4.5-fold increase in RVFV MP12-GFP (MOI of 0.3) infection, while VSV infection remained unchanged with similar concentrations and infection conditions." (PMID 27226375, 2016). "Infection with H. pylori as well as treatment with recombinant Wnt3a, but not heat-killed H. pylori strongly induced protein expression of Axin2." (PMID 20137080, 2010). "Taken together, these data demonstrate that HIEs from multiple intestinal segments can be successfully differentiated by withdrawal of WNT3A, but that the differentiation status of HIE does not alter susceptibility to VA1 and infection does not induce HIE differentiation." (PMID 31671153, 2019).
adenocarcinoma (4 papers, 2019 to 2024). A common cancer characterized by the presence of malignant glandular cells. "In the CAC model mice, we observed Wnt3a, Wnt5a, β‐catenin, and non‐phosphorylated (activated) β‐catenin were markedly upregulated in early adenocarcinoma tissues." (PMID 39302044, 2024). "The study found significant molecular changes in adenocarcinoma tissues from a CAC mouse model, including increased expression of Wnt3a and Wnt5a proteins, total β‐catenin protein, and activated β‐catenin." (PMID 39302044, 2024). "Wnt3a promotes the formation of a myofibroblast-like phenotype in cultured fibroblasts, in part, by upregulating TGF-β signaling, whereas studies in mice show that stromal Wnt3a activates canonical Wnt signaling in the epithelium, facilitating progression of PIN lesions to adenocarcinoma." (PMID 39335188, 2024).
Cardiovascular Diseases (3 papers, 2021 to 2025). "The Wnt3a‐mediated canonical Wnt pathway within the Wnt family has been extensively investigated in cardiovascular disease." (PMID 40407710, 2025).
colon polyps (2 papers, 2019 to 2024). "This is the first study analyzing the gene expression of APC, Wnt3A, Wnt5A, BCL9, and LEF1 in the colon polyps vs. adjacent mucosa and vs. normal mucosa from control individuals." (PMID 39200196, 2024).
kidney disease (2 papers, 2020 to 2025). "The Wnt3a/β-catenin pathway plays a crucial role in podocyte injury and the pathogenesis of kidney disease." (PMID 39028478, 2025). "The potential roles of other wnt molecules in brain except wnt3a in renal diseases remain unknown." (PMID 31392659, 2020).
neurodegenerative disease (1 paper, 2020). A disorder of the central nervous system characterized by gradual and progressive loss of neural tissue and neurologic function. "First, microglial exosomes could be released in response to WNT3A, which is a signaling factor that has been implicated in several neurodegenerative diseases, including AD." (PMID 31843449, 2020).
WNT3A also shares sentences with these, for which no sentence is quoted: malignant mesothelioma (4 papers); multiple myeloma (3); ulcerative colitis (3); atrial fibrillation (2); B-cell acute lymphoblastic leukaemia (2); bacterial infection (2); neuronal tumor (2); psoriasis (2); schistosomiasis (2); schwannoma (2); small cell lung carcinoma (2); tendinopathy (2); triple-negative breast carcinoma (2); allergic rhinitis (1); Arthritis (1); autoimmune disease (1); Azoospermia (1); brain injury (1); brain tumours (1); cannabis dependence (1); central nervous system diseases (1); chondrosarcoma (1); chronic kidney disease (1); colorectal adenoma (1); ductal carcinoma in situ (1); End Stage Liver Disease (1); Endotoxemia (1); esophageal adenocarcinoma (1); essential hypertension (1); hyperglycaemia (1).
A further 29 diseases each share a sentence with WNT3A in 1 paper.